SIRT1 (sirtuin 1)
Diseases named in the same sentence as SIRT1 in open-access papers (continued):
Sharing a sentence is not in itself a finding about the gene and the disease.
Insulin resistance (continued). "SIRT1 binds and deacetylates PPARγ, which helps recruit the BAT program coactivator PRDM16 to PPARγ, leading to selective induction of BAT genes associated with browning of white adipocytes and repression of visceral WAT genes associated with insulin resistance." (PMID 35743009, 2022). "Furthermore, Sirt1 activity in the liver affects gluconeogenesis and insulin resistance." (PMID 35132380, 2022). "Therefore, it can be speculated that resveratrol can inhibit FOXO1 expression through SIRT1, thereby improving insulin resistance and restoring normal blood glucose levels." (PMID 35739982, 2022). "However, whether VD-deficient signaling in the liver increases gluconeogenesis and insulin resistance or triggers the dysregulation of Sirt1 activity is unknown." (PMID 35132380, 2022). "CR delays development of insulin resistance, glucose intolerance, and dyslipidemia in the adipose tissue of normal mice, whereas lack of functional SIRT1 increases the incidence of those outcomes, indicating a role for SIRT1 against development of MetS-related symptoms." (PMID 33806509, 2021). "However, whether its ability to ameliorate skeletal muscle insulin resistance (IR) is through modulation of the AMPK/SIRT1/PGC-1α signaling pathway remains unknown." (PMID 34326919, 2021). "Thus, SIRT1 may improve insulin resistance by reducing oxidative stress and regulating mitochondrial biogenesis and function." (PMID 34746831, 2021). "A negative correlation between SIRT1 gene expression levels and BMI values of patients was previously shown and this was also associated with more pro-inflammatory gene expression contributing to insulin resistance." (PMID 34804028, 2021). "In addition, SIRT1 deletion in myeloid cells increased the infiltration of M1 macrophages and decreased M2 macrophages in adipose tissue in mice on high-fat diets, resulting in insulin resistance that is present in our FRD model." (PMID 33976753, 2021). "Overexpression of miR-181a levels were found in insulin-resistant cultured hepatocytes, and inhibition of miR-181a may lead to increased protein levels of SIRT1, which is a potential therapeutic target for combating insulin resistance, and thereby improving hepatic insulin sensitivity." (PMID 34006268, 2021). "In animal models, it was demonstrated that mice with SIRT1 adipocyte-specific knockout gained weight rapidly, along with glucose intolerance and insulin resistance compared with control mice, while the SIRT1 agonist resveratrol could prevent or ameliorate glucose and lipid metabolic disturbance." (PMID 33324265, 2020). "In addition, the HFD-fed Sirt1 heterozygous mice (Sirt1+/–) present with more severe insulin resistance, compared with wild-type mice, which may be mediated by reductions in adipose GLUT4 translocation and insulin-stimulated glucose transport." (PMID 33193730, 2020). "SIRT1 could regulate the gluconeogenic/glycolytic pathways in liver in response to maintain blood glucose levels, and activation of SIRT1 can significantly inhibit the ROS and NO production, and improve the oxidative stress-related insulin resistance." (PMID 32493421, 2020). "Furthermore, SIRT1 knockout mice fed with a high-fat diet leads to activation of macrophages and another inflammatory mediator in the liver which related to the development of insulin resistance." (PMID 32815547, 2020). "Thus, SIRT1 may improve insulin resistance and T2DM possibly through reducing oxidative stress, inducing mitochondrial biogenesis, and increasing mitochondrial function." (PMID 30972029, 2019). "Thus, the activation of SIRT1 may improve insulin resistance through promoting fatty acid oxidation and mitochondrial biogenesis via deacetylation of PGC-1α and PPAR-α activation in skeletal muscle." (PMID 30972029, 2019). "Thus, SIRT1 may diminish inflammation in adipose tissues and monocytes/macrophages and may improve insulin resistance and T2DM." (PMID 30972029, 2019).
Insulin resistance (continued). "Therefore, interventions that increase SIRT1 activity may be beneficial in improvement of insulin resistance and control of DM." (PMID 29343256, 2018). "Consequently, metformin therapy reducing hyperglycemia and insulin resistance, may revert the systemic inflammation/oxidative stress in obese patients with prediabetic condition with SIRT1 modulation." (PMID 30246793, 2018). "Our results further show different metabolic regulations in groups A and B, which may be due to differences in expression of SIRT1, glucose transfer or insulin resistance as a result of resistance to glucose entry to fetal tissues for unknown reasons, which require further studies." (PMID 29971183, 2018). "Also, SIRT1 is thought to be a key of regulating skeleton muscle metabolism and that decreased SIRT1 expression may contribute to insulin resistance." (PMID 27659520, 2017). "SIRT1 is an NAD-dependent deacetylase (histone deacetylase (HDAC)) that has been linked to many beneficial effects of cellular processes including gene silencing, insulin resistance, glucose homeostasis, fatty acid metabolism, and aging, while HAT catalyses the opposite reaction." (PMID 28074114, 2016). "Hence, the aim of the current study was to investigate whether SIRT1 overexpression would prevent the development of insulin resistance in skeletal muscle in vivo." (PMID 25798922, 2015). "Thus, combining the results from cell work and the muscle strip experiments, it is possible that SIRT1 may contribute to hyperglycemia-induced insulin resistance." (PMID 25798922, 2015). "Furthermore, the histone deacetylase (HDAC) SIRT1, by virtue of its role in inflammatory responses, adipokine secretion and its interaction with the insulin signaling pathway, is suggested to have therapeutic benefit in treating insulin resistance." (PMID 21655096, 2011). "NNMT exhibited tissue-specific duality, whereby hepatic upregulation promoted SIRT1 stabilization, improved lipid profiles, and guarded against NAFLD progression, whereas adipose upregulation depleted methyl donors and fostered insulin resistance." (PMID 40869253, 2025). "hsa-miR-34a-5p regulates lipogenesis and adipocyte differentiation through SIRT1 (sirtuin 1) and PPARG suppression, linking it to visceral fat accumulation and insulin resistance." (PMID 40699679, 2025). "Reduces inflammation, improves gut microflora, alleviates insulin resistance (PI3K/AKT/GLUT4, FOXO1), reduces inflammatory markers, promotes muscle growth (MyHC, Sirt1, PGC-1α, MEF2C, AMPK)." (PMID 41404330, 2025). "SIT treatment was associated with increased expression of insulin receptor one and decreased expression of makers for insulin resistance, including phospho-PKC- alpha, RBP-4, SIRT1, and PI3K (p<0.05)." (PMID 39074126, 2024). "Administration of the SIRT1 activator resveratrol can restore the phosphorylation level of AMPK, inhibit the IKKβ/NF-κB pathway, and thus improve insulin resistance." (PMID 38745862, 2024). "Sirtuins, including SIRT1, SIRT2, SIRT3, and SIRT6, play crucial roles in regulating cellular metabolism, and their dysregulation contributes to insulin resistance and diabetes, notably affecting skeletal muscle." (PMID 38904020, 2024). "Supplementation with RA increases the expressions of the mitochondrial biogenesis genes like PGC-1α, SIRT1, and TFAM through activation of AMPK in the skeletal muscles of rats with insulin resistance as well as in L6 myotubes." (PMID 38903985, 2024). "This ability of chlorella to modulate insulin signaling pathways seems to also be related to its activity on muscle sirtuin 1 (SIRT1), as increased expression of SIRT1 improves insulin sensitivity and attenuates insulin resistance." (PMID 37432326, 2023). "Modulation of SIRT1/AMPK and Akt/mTOR pathways is crucial in reducing insulin levels, insulin resistance, glucotoxicity and lipotoxicity, and in increasing ketogenesis." (PMID 37152929, 2023).
Insulin resistance (continued). "Further the downregulation of IRS-1, SIRT1 and GLUT-4 and upregulation of ADAM 17 demonstrates its potential impact on glucose homeostasis, insulin resistance and chronic inflammatory markers." (PMID 37089941, 2023). "Upregulation of miR‐146b decreases Sirt1 gene expression and subsequent acetylation of FOXO1 in diabetic mice liver and HepG2 cells, in response to the insulin resistance induction and the suppression of hepatic glycogenesis." (PMID 37329278, 2023). "PCOS patients generally have insulin resistance, and IGF1 can enhance pancreatic β cell viability and inhibit apoptosis by activating the Sirt1/PI3K/Akt/FoxO1 pathway, inducing insulin secretion, and alleviating oxidative damage." (PMID 37701184, 2023). "Further upregulation of IRS-1, SIRT1, GLUT-4 and downregulation of ADAM17, demonstrated its potential impact on glucose homeostasis, insulin resistance and chronic inflammatory markers." (PMID 37089941, 2023). "For example, the intraperitoneal administration of NMN restores NAD+ biosynthesis and improves glucose intolerance, insulin resistance, and dyslipidemia in age- or HFD-induced diabetic mice by activating SIRT1-catalyzed reactions." (PMID 36986224, 2023). "SIRT1 has the ability to control PGC-1α deacetylation, which activates peroxisome proliferator-activated receptor-α (PPAR-α), leading to enhanced insulin resistance and increased fatty acid oxidation." (PMID 38001474, 2023). "In one of the studies on rats on a high-fat diet with induced insulin resistance, the effect of BBR on hepatic metabolism with the participation of the PI3K/Akt-p/SIRT1/PTEN pathway was demonstrated." (PMID 37630770, 2023). "PPARγ/SREBP-1c pathways are involved in alleviation of Antrodan-treated NAFLD via upregulated pAMPK and Sirt1, and downregulated PPARγ and SREBP-1c, thereby suppressing lipid biosynthesis and facilitating insulin resistance." (PMID 36552896, 2022). "In vivo experiments showed that DEL-1 administration increased the expression of SIRT1 and SERCA2, thereby ameliorating insulin resistance in skeletal muscle of high fat diet (HFD)-fed mice and improving HFD-impaired glucose tolerance and insulin sensitivity." (PMID 36518760, 2022). "After 22 weeks of treatment, both SIRT1 and NAD+/NADH were down-regulated in the ethanol treatment group, while resveratrol ameliorated these down-regulation and improved insulin resistance." (PMID 35739982, 2022). "SIRT1 deacetylates lysine residues of PGC-1α and PPARγ, promotes WACs browning, and improves insulin resistance." (PMID 35416120, 2022). "Previous animal experiments have shown that the acupoints CV4 and SP6 can activate SIRT1/PGC-1α in skeletal muscle and regulate the expression of key insulin signaling-related molecules, thus relieving insulin resistance in obese diabetic mice." (PMID 35903320, 2022). "Activation of SIRT1 inhibits the expression of intracellular uncoupling protein-1 (UCP-1), further leading to increased insulin secretion and improved insulin resistance." (PMID 35739982, 2022). "SIRT1 knockout in adipocytes of HFD-fed mice initially leads to glucose intolerance, hyperinsulinemia and insulin resistance faster than in wild type mice." (PMID 33806509, 2021). "In mouse models of insulin resistance, GQD alleviated insulin resistance through silent information regulator 1 (Sirt1)-dependent deacetylation of forkhead box O1 (FOXO1)." (PMID 34025427, 2021). "AS101, a tellurium compound, has been found to reverse insulin resistance and attenuate T2DM in rats by triggering SIRT1 activation and deacetylation function." (PMID 34071497, 2021). "To summarize, our results demonstrate that calystegines from Hyoscyamus albus provide cytoprotection to the HepG2 cells against insulin/glucose induced insulin resistance and apoptosis due to activation of PI3K/AKT and SIRT1/NF-kB/JNK signalling pathways." (PMID 34034759, 2021).
Insulin resistance (continued). "In mature adipocytes, SIRT1 promotes fat mobilization through repression of PPARγ and protects cells from TNF-alpha-induced insulin resistance." (PMID 34863096, 2021). "Resveratrol also improved endothelial dysfunction in obese and diabetic mice through SIRT1/PPAR pathway, and improved glucose absorption in adipocytes with insulin resistance." (PMID 35047575, 2021). "As a circadian upstream factor of SIRT1, NAMPT is involved in insulin resistance through PPARγ and adiponectin." (PMID 32334629, 2020). "Thus, VD may decrease insulin resistance by increasing SIRT1 and Irisin." (PMID 32033527, 2020). "L-O2 cells were cultured as a model of insulin resistance, and MNAM and SIRT1 inhibitors were administered in vivo." (PMID 32280711, 2020). "Overexpression of Sirt1 and various Sirt1 activators stimulate AMPK signaling, leading to improved insulin resistance in adipocytes and muscle tissue." (PMID 33390968, 2020). "SIRT1 protects against inflammation and TNFA induced insulin resistance, whilst also promotes glucose uptake and insulin signaling in murine adipocytes." (PMID 33207733, 2020). "It has been shown, that under pathophysiological conditions such insulin resistance and metabolic dysfunction FoxO1 expression may help drive the expression of genes involved in combating oxidative stress and that there is interplay between SirT1 and FoxO in ROS reduction." (PMID 33344504, 2020). "Hyperandrogenism resulted in the negative regulation of BMAL1-induced expression of the NAMPT/NAD+/SIRT1 pathway, which further suppressed GLUT4, leading to insulin resistance in the liver and adipose tissues of rats." (PMID 32334629, 2020). "Among these, SIRT1 and SIRT2 were known as class I in sirtuin family, which exerted diverse influence on lifespan, insulin resistance, and metabolism." (PMID 32781630, 2020). "Metformin has been reported to reduce insulin resistance by activating AMPK and SIRT1 to inhibit hepatic gluconeogenesis, suppress lipid biosynthesis, and enhance glucose metabolism, thus decreasing circulating glucose and lipid levels." (PMID 32697764, 2020). "Additionally, myeloid cell-specific SIRT1 knockout (KO) mice that were fed a high-fat diet (HFD) exhibited macrophage activation and elevated expression of inflammatory mediators in the liver and adipose tissues, which was associated with the development of systemic insulin resistance." (PMID 30972029, 2019). "SIRT1 may play a crucial role in reducing inflammation and oxidative stress and improving mitochondrial function, resulting in both the protection of pancreatic β cells and amelioration of insulin resistance in insulin-sensitive tissues such as skeletal muscle and adipose tissue." (PMID 30972029, 2019). "Different polyphenols such as berberine and resveratrol have previously been shown to induce SIRT1 expression in different models of NAFLD and insulin resistance." (PMID 30832407, 2019). "It's worth noting that SIRT1, SIRT2, SIRT3, and SIRT6 are positive regulators of insulin resistance in most cases." (PMID 30559718, 2018). "Studies have shown that dietary polyphenols by stimulation of SIRT1 activity result in the suppression of NF-κB and activation of PGC-1α; hence improving insulin resistance and lipid metabolism." (PMID 29343256, 2018). "On the contrary, SIRT1 overexpression in SF1 neurons prevented from diet-induced obesity and insulin resistance." (PMID 30405528, 2018). "Nevertheless, blunt of SIRT3 and SIRT1 in C2C12 cells impairs insulin pathway and stimulates insulin resistance." (PMID 30559718, 2018). "Our studies showed an important role for SIRT1 and mitochondrial biogenesis in the preventive effects of BBR on diet-induced insulin resistance." (PMID 29351246, 2018). "High AGE-containing diets induce insulin resistance; on the other side, AGE restriction in food ameliorates insulin signaling, and increases sirtuin-1 expression and AGER-1 that mitigate deleterious gene expression elicited by the AGE/RAGE axis." (PMID 29018354, 2017).
Insulin resistance (continued). "Lifestyle manipulations, such as CR and exercise, can reverse insulin resistance and T2DM and share common mechanistic pathways of AMPK activation leading to elevated NAMPT-mediated NAD+ generation and SIRT1 activity to enhance mitochondrial function." (PMID 29264533, 2017). "Inhibition of SIRT1 by EX527 significantly eliminated the downregulation of the inflammation and insulin-resistance levels induced by the miR-377 inhibitor." (PMID 29050301, 2017). "Inhibition of SIRT1 by EX527 significantly eliminated the downregulation of the inflammation and insulin-resistance induced by the miR-377 inhibitor." (PMID 29050301, 2017). "Gomes and colleagues revealed the critical role for SIRT1 and mitochondrial biogenesis in the preventive effect of BBR on diet-induced insulin resistance." (PMID 26788242, 2016). "SIRT1 over-expression or SIRT1 activation can reduce both PTP1B mRNA and protein levels during insulin-resistance." (PMID 23203037, 2012). "Simultaneously, insulin resistance downregulates key mitochondrial regulators including peroxisome proliferator-activated receptor gamma coactivator 1-alpha (PGC-1α) and sirtuin 1 (SIRT1), leading to impaired oxidative phosphorylation and cellular energy homeostasis." (PMID 40759963, 2025). "Similarly, NMN treatment can ameliorate insulin resistance induced via a high fat diet by restoring NAD+ biosynthesis and SIRT1/SIRT3 activity." (PMID 38256175, 2024). "Moreover, PDX was shown to ameliorate hepatic insulin resistance by modulating fetuin-A and SeP expression via the AMPK/SIRT1 pathway." (PMID 39273541, 2024). "Previous research has shown that RS could relieve insulin resistance through the Sirt1-p-AMPK-p-AKT and Sirt1-p-IRS-1-p-AKT pathways in adipocytes, thereby promoting glucose uptake through increased membrane accumulation of Glut4." (PMID 38903985, 2024). "Among other effects, PA induces insulin resistance, increases intracellular calcium and reactive oxygen species (ROS) production, and reduces the NAD+/NADH ratio, resulting in decreased activity of the deacetylase Sirtuin1 (SIRT1) in neurons." (PMID 38167971, 2024). "Gluconeogenesis disorder is the most typical feature of insulin resistance in which HNF-4α synergizes with PGC-1α, FOXO1 and other key enzymes to induce gluconeogenesis, and Leptin regulates the AMPK pathway by inhibiting HNF-4α and promoting SIRT1 expression." (PMID 37705071, 2023). "On the other hand, when SIRT1 is stimulated, it deacetylates and activates the LKB1 protein kinase, which phosphorylates and activates AMPK, thereby attenuating oxidative damage, improving insulin resistance and restoring energy homeostasis." (PMID 37108584, 2023). "Likewise, NMN treatment ameliorates HFD-induced insulin resistance by restoring NAD+ biosynthesis and SIRT1/SIRT3 activity." (PMID 35563288, 2022). "SIRT1 also represses PTP1B transcription and affects insulin resistance." (PMID 35517847, 2022). "Activation of SIRT1/AMPK can improve liver injury in NAFLD by regulating lipid metabolism, relieving inflammation, and attenuating endoplasmic reticulum stress and insulin resistance." (PMID 34681600, 2021). "Finally, local insulin sensitivity is affected by expressions of SIRT1 and SIRT3, which reduce insulin resistance." (PMID 33806509, 2021). "Other AMPK activators such as berberine and salidroside can significantly up-regulate the expression of phosphorylated AMPK, promote mitochondrial quality, improve insulin resistance and glucose uptake through stimulating AMPK/SIRT1 and its downstream signaling pathway." (PMID 34616289, 2021). "SIRT1 decreases insulin resistance, likely through multiple routes since, alone, it is not sufficient to generate an effect." (PMID 33806509, 2021). "Furthermore, the inhibition of AMPK, SIRT‐1 and PGC‐1α reversed the beneficial effects of FGF19 on mitigating PA‐ and HFD‐induced lipid droplet accumulation and insulin resistance." (PMID 33751819, 2021).